MAPK8IP3 (mitogen-activated protein kinase 8 interacting protein 3)
Description:
The JNK-interacting protein (JIP) group of scaffold proteins selectively mediates JNK signaling by aggregating specific components of the MAPK cascade to form a functional JNK signaling module. May function as a regulator of vesicle transport, through interactions with the JNK-signaling components and motor proteins (By similarity). Promotes neuronal axon elongation in a kinesin- and JNK-dependent manner. Activates cofilin at axon tips via local activation of JNK, thereby regulating filopodial dynamics and enhancing axon elongation. Its binding to kinesin heavy chains (KHC), promotes kinesin-1 motility along microtubules and is essential for axon elongation and regeneration. Regulates cortical neuronal migration by mediating NTRK2/TRKB anterograde axonal transport during brain development (By similarity). Acts as an adapter that bridges the interaction between NTRK2/TRKB and KLC1 and drives NTRK2/TRKB axonal but not dendritic anterograde transport, which is essential for subsequent BDNF-triggered signaling and filopodia formation.
Synonyms: JIP-3; JIP3; KIAA1066; JSAP1; syd; NEDBA; SYD2
Tractability: Small molecule: a structure with a bound ligand is known. PROTAC: ubiquitination databases record sites on it; its protein half-life has been measured.
Gene: Protein-coding gene on chromosome 16 (1,706,166 to 1,770,351, forward strand). Ensembl gene ENSG00000138834.
Subcellular location: Cytoplasm; Golgi apparatus; Cytoplasmic vesicle; Cell projection, growth cone; Cell projection, axon; Cell projection, dendrite; Cytoplasm, perinuclear region
Subcellular location (Human Protein Atlas): Vesicles; Centrosome; Cytokinetic bridge; Cytosol
Gene Ontology:
Molecular function: protein binding; JUN kinase binding; kinesin binding; MAP-kinase scaffold activity; signaling receptor complex adaptor activity
Biological process: negative regulation of apoptotic process; protein stabilization; anterograde axonal protein transport; axon development; axon regeneration; positive regulation of JNK cascade; regulation of JNK cascade; vesicle-mediated transport; MAPK cascade
Cellular component: axon; cell body; cytoplasm; cytoplasmic vesicle; dendrite; Golgi apparatus; Golgi membrane; perinuclear region of cytoplasm; axon cytoplasm; growth cone
Genetic constraint (gnomAD): Loss-of-function variants: 49 observed, 152.88 expected, observed/expected ratio (o/e) 0.32, 90% interval 0.25 to 0.41. The upper end of that interval is the gene's LOEUF score, 0.41, which puts it in group 1 of 6, group 1 being the genes least tolerant of losing a copy. Missense variants: 1,478 observed, 1,886.2 expected, observed/expected ratio (o/e) 0.78, 90% interval 0.75 to 0.82. Synonymous variants: 897 observed, 780.97 expected, observed/expected ratio (o/e) 1.15, 90% interval 1.09 to 1.21.
Gene-disease validity (ClinGen):
ClinGen rates the evidence that MAPK8IP3 causes each of these diseases.
neurodevelopmental disorder with or without variable brain abnormalities; NEDBA (autosomal dominant): Definitive.
Homologues: Orthologues: macaque MAPK8IP3 (99% identical), rat Mapk8ip3 (94% identical), guinea pig MAPK8IP3 (94% identical), mouse Mapk8ip3 (94% identical), chimpanzee MAPK8IP3 (94% identical), dog MAPK8IP3 (93% identical), pig MAPK8IP3 (93% identical), tropical clawed frog mapk8ip3 (85% identical), zebrafish mapk8ip3 (71% identical), Drosophila melanogaster syd (40% identical), Caenorhabditis elegans unc-16 (34% identical). Paralogues in human: SPAG9 (58% identical).
Diseases named in the same sentence as MAPK8IP3 in open-access papers:
MAPK8IP3 is named in the same sentence as 26 diseases in open-access papers, as found by Europe PMC text mining. Sharing a sentence is not in itself a finding about the gene and the disease. The quoted sentences say what the papers report.
Intellectual disability (3 papers, 2022 to 2024). "Recent studies have identified multiple de novo variants in JIP3/MAPK8IP3 which are associated with a neurodevelopmental disorder presenting with mild to severe intellectual disability and other brain anomalies." (PMID 39632089, 2024). "Since de novo variants in MAPK8IP3 have recently been linked to a neurodevelopmental disorder with intellectual disability, there is a need to better understand the functioning of this protein in human neurons." (PMID 35711470, 2022). "In recent years, two independent studies identified de novo variants in MAPK8IP3 in individuals presenting with intellectual disability as well as brain anomalies including perisylvian polymicrogyria, cerebral or cerebellar atrophy, and hypoplasia of the corpus callosum." (PMID 35711470, 2022). "Future work will focus on elucidating other molecular machinery that acts in concert with MAPK8IP3 in this pathway, as well as whether MAPK8IP3 variants linked with intellectual disability affect this pathway in neurons." (PMID 35711470, 2022). "Given two independent and recent studies have implicated de novo variants in MAPK8IP3 as a cause of a neurodevelopmental disease with intellectual disability and variable brain anomalies, identifying neuronal cellular processes altered by changes to MAPK8IP3 is critical." (PMID 35711470, 2022). "In addition to advancing our knowledge about fundamental aspects of cell function, these studies may provide new insight into mechanisms relevant to Alzheimer’s disease pathology as well as to human intellectual disabilities arising from mutations in the MAPK8IP3/JIP3 gene." (PMID 35013510, 2022).
developmental delay (2 papers, 2023 to 2024). "Notably, according to gnomAD, eleven out of > 140.000 individuals are predicted to carry heterozygous LoF variants in MAPK8IP3, indicating that pathogenic variants associated with developmental delay are not caused by LoF but rather gain of function variants." (PMID 37330543, 2023).
acanthosis nigricans (1 paper, 2022). A melanotic cutaneous lesion that develops in the axilla and other body folds. "In addition to the cases mentioned in this paper, other rare disorders that have matched with therapeutic options include non-ketotic hyperglycinemia, MAPK8IP3-related disorder, EGFR-associated acanthosis nigricans, and SETD1A-related disorder." (PMID 36248623, 2022).
Arthritis (1 paper, 2024). Inflammation of a joint. "Moreover, our ROC curve analysis results indicated that the differential expression of HLA-DQA1 and MAPK8IP3 could be potential biomarkers of both arthritis forms." (PMID 39315289, 2024).
axonal neuropathy (1 paper, 2020). Any nerve disorder affecting the axon of a nerve. "Our results also show that mitogen-activated protein kinase 8 interacting protein 3 (MAPK8IP3), recently implicated in nerve degeneration and axonal neuropathy, is hypomethylated and upregulated in group 1 compared to group 2." (PMID 32787975, 2020). "In addition to its emerging role in nerve degeneration and axonal neuropathy, MAPK8IP3 may be an important player in the progression of human DPN through its close interaction with Toll-like receptor 4 (TLR4) and JNKs." (PMID 32787975, 2020).
cognitive deficits (1 paper, 2024). "Mapk8ip3 (JIP-3) is a scaffold protein regulating JNK activation with rare missense mutations causing cognitive deficits implicated in the regulation of axonal transport of dynein and kinesin-1 and bi-directional cargo, including lysosomes." (PMID 38542311, 2024).
lung carcinoma (1 paper, 2021). "Therefore, MAPK8IP3 may have the potential to be recognized as a novel biomarker in lung cancer investigation." (PMID 33765916, 2021). "In our analysis, we also identified MAPK8IP3 as a novel and potent target that has not been reported in previous lung cancer studies." (PMID 33765916, 2021). "In addition, MAPK8IP3 gene was identified as a novel gene, which has not been reported in previous lung cancer studies and may have the potential to be recognized as a novel biomarker in lung cancer investigation." (PMID 33765916, 2021).
prostate carcinoma (1 paper, 2022). A carcinoma that arises from epithelial cells of the prostate gland. "Previous studies indicated that MAPK8IP3 may be associated with the malignant progression of prostate cancer." (PMID 36357836, 2022).
tumor (6 papers, 2020 to 2024). "Our study found that HNRNPA2B1, GOLGA8B and MAPK8IP3 were identified to be tightly associated with tumour progression and prognosis, and further researches are needed before clinical application." (PMID 32485038, 2020). "Eventually, HNRNPA2B1, GOLGA8B and MAPK8IP3 were picked out to be significantly associated with tumour prognosis." (PMID 32485038, 2020). "Exosomes derived from M2 type tumor-associated macrophages could promote Osimertinib resistance in NSCLC via the MSTRG.292666.16-miR-6836-5p-MAPK8IP3 axis." (PMID 38326804, 2024). "Additionally, HNRNPA2B1, GOLGA8B and MAPK8IP3 were identified to be tightly associated with tumour progression and prognosis." (PMID 32485038, 2020). "Notably, MAPK8IP3 (JIP3) had a significant negative correlation with retrograde trafficking genes, whilst SPAG9 (JIP4) had a significant positive correlation, in GP3 and GP4 tumours." (PMID 39217195, 2024).
cancer (4 papers, 2022 to 2024). A tumor composed of atypical neoplastic, often pleomorphic cells that invade other tissues. "Our results showing reduced Dextran and BSA uptake in MAPK8IP3 KO i3Neurons could suggest that MAPK8IP3 plays a similar role in regulating macropinocytosis as observed previously in cultured cancer lines." (PMID 35711470, 2022). "The MAPK signaling pathway has been shown to be activated in many cancers that are resistant to drugs, and our study found that RPS6KA1, CACNA1B, and MAPK8IP3 were significantly enriched in the MAPK signaling pathway." (PMID 35168607, 2022). "Hence, the activation of the identified DEGs (MAPK4, MAPK15, and MAPK8IP3) might trigger the MAPK pathway and thereby influence drug resistance during cancer therapy." (PMID 37415453, 2023).
neurodevelopmental disorder (3 papers, 2022 to 2025). A behavioral and cognitive disorder with onset during the developmental period that involves impaired or aberrant development of intellectual, motor, or social functions. "Given variants of MAPK8IP3 are linked to a neurodevelopmental disorder, identifying more neuronal cellular processes that are regulated by MAPK8IP3 will help us understand the neurodevelopmental pathology associated with the different variants." (PMID 35711470, 2022). "The study by Platzer and colleagues that identified 13 de novo variants in MAPK8IP3 through exome sequencing of 27,232 individuals (majority of whom had been diagnosed with a neurodevelopmental disorder), also examined the effect of some of these variants on axonal lysosome abundance in C. elegans." (PMID 35711470, 2022). "De novo variants in MAPK8IP3, a putative adaptor protein believed to link cargo to dynein and kinesin motors, have been found in children with neurodevelopmental disorders." (PMID 35711470, 2022). "Our findings indicate that MAPK8IP3 may be a regulator of bulk endocytosis in neurons and that altered endocytic uptake may play a role in MAPK8IP3-linked neurodevelopmental disorders." (PMID 35711470, 2022).
MAPK8IP3 also shares sentences with these, for which no sentence is quoted: breast carcinoma (2 papers); infection (2); non-small cell lung carcinoma (2); Alzheimer disease (1); amyloid (1); autism (1); Brain Abnormalities (1); cardiac hypertrophy (1); Cirrhosis (1); colon carcinoma (1); dementia (1); depression (1); neurodegenerative disease (1); neurological disease (1); prostate tumours (1).